SCN7A (sodium voltage-gated channel alpha subunit 7)
Description:
Sodium leak channel functioning as an osmosensor regulating sodium ion levels in various tissues and organs. While most sodium channels are voltage-gated, SCN7A is not and lets sodium flow through membrane along its concentration gradient. In glial cells of the central nervous system, senses body-fluid sodium levels and controls salt intake behavior as well as voluntary water intake through activation of nearby neurons to maintain appropriate sodium levels in the body (By similarity). By mediating sodium influx into keratinocytes, also plays a role in skin barrier homeostasis.
Synonyms: SCN6A; Nav2.1; Nav2.2; NaG
Tractability: Small molecule: an approved drug acts on it; a structure with a bound ligand is known; a high-quality ligand is known; it belongs to a druggable protein family. Antibody: UniProt places it where antibodies can reach, with high confidence; UniProt predicts a signal peptide or a membrane-spanning region; its Gene Ontology location is reachable by antibodies, with medium confidence; the Human Protein Atlas places it where antibodies can reach. PROTAC: a small molecule that binds it is known.
Target class: Voltage-gated ion channel; Voltage-gated sodium channel; Ion channel
Gene: Protein-coding gene on chromosome 2 (166,403,472 to 166,611,482, reverse strand). Ensembl gene ENSG00000136546.
Subcellular location: Cell membrane
Subcellular location (Human Protein Atlas): Plasma membrane
Pathways (Reactome):
Developmental Biology: Interaction between L1 and Ankyrins
Muscle contraction: Phase 0 - rapid depolarisation
Gene Ontology:
Molecular function: protein binding; sodium channel activity; osmolarity-sensing monoatomic cation channel activity; voltage-gated sodium channel activity; monoatomic cation channel activity; monoatomic ion channel activity; transmembrane transporter binding
Biological process: sodium ion homeostasis; cardiac muscle cell action potential involved in contraction; osmosensory signaling pathway; regulation of membrane potential; sodium ion transmembrane transport; monoatomic ion transport; sodium ion transport; transmembrane transport
Cellular component: cation channel complex; plasma membrane; voltage-gated sodium channel complex; glial cell projection; membrane
Genetic constraint (gnomAD): Loss-of-function variants: 94 observed, 99.24 expected, observed/expected ratio (o/e) 0.95, 90% interval 0.8 to 1.12. The upper end of that interval is the gene's LOEUF score, 1.12, which puts it in group 4 of 6, group 1 being the genes least tolerant of losing a copy. Missense variants: 1,653 observed, 1,602.2 expected, observed/expected ratio (o/e) 1.03, 90% interval 0.99 to 1.07. Synonymous variants: 569 observed, 525.62 expected, observed/expected ratio (o/e) 1.08, 90% interval 1.01 to 1.16.
Homologues: Orthologues: chimpanzee SCN7A (99% identical), dog SCN7A (80% identical), pig SCN7A (79% identical), rabbit SCN7A (75% identical), mouse Scn7a (74% identical), rat Scn7a (73% identical), guinea pig SCN7A (69% identical). Paralogues in human: SCN9A (56% identical), SCN2A (54% identical), SCN3A (53% identical), SCN1A (53% identical), SCN8A (51% identical), SCN4A (50% identical), SCN5A (48% identical), SCN10A (45% identical), SCN11A (40% identical), CACNA1C (24% identical), CACNA1D (23% identical), CACNA1S (23% identical), and 14 more.
Diseases named in the same sentence as SCN7A in open-access papers:
SCN7A is named in the same sentence as 37 diseases in open-access papers, as found by Europe PMC text mining. Sharing a sentence is not in itself a finding about the gene and the disease. The quoted sentences say what the papers report.
Alzheimer disease (1 paper, 2023). A progressive, neurodegenerative disease characterized by loss of function and death of nerve cells in several areas of the brain leading to loss of cognitive function such as memory and language. "Some of these genes have already been linked to serious neurological conditions, such as SCN7A, which has been associated with amyotrophic lateral sclerosis, GLIS1 with Parkinson’s Disease and SPARCL1 with neuroinflammation in Alzheimer’s Disease." (PMID 36980268, 2023).
cervical cancer (1 paper, 2022). A primary or metastatic malignant neoplasm involving the cervix. "These target genes were crossed with mRNAs that are downregulated by more than fivefold in cervical cancer from The Cancer Genome Atlas (TCGA) database, and 8 target genes were finally obtained (OGN, SCN7A, PGR, PTGER3, FGF7, ADAMTS5, LMO3 and ANK2)." (PMID 35513835, 2022).
colorectal carcinoma (1 paper, 2020). A malignant epithelial neoplasm that arises from the colon or rectum and invades through the muscularis mucosa into the submucosa. "SCN7A encodes a voltage-dependent sodium channel of the excitable membrane, and it is reported to be downregulated in colorectal carcinoma at the mRNA level." (PMID 33102522, 2020).
erythromelalgia (1 paper, 2016). A rare neurovascular peripheral pain disorder due to the intermittent blockage of the blood vessels, usually in the lower extremities or hands. "Recently, rare variants of genes other than SCN9a were described in patients with clinically verified erythromelalgia: those genes included SCN10A (Nav1.8), SCN11A (Nav1.9), SCN5A (Nav1.5), SCN7A (Nav2.1), SCN8A (Nav1.6), SCN1B (Nav β1 subunit), SCN3B (Nav β3 subunit), TRPA1, TRPV1, WNK1 and NGFR." (PMID 27598514, 2016).
gastric cancer (1 paper, 2022). A primary or metastatic malignant neoplasm involving the stomach. "In conclusion, our study demonstrated that SCN7A mutations in gastric cancer may be associated with higher TMB and improved patient outcomes." (PMID 35123417, 2022). "Therefore, we reasoned that expression level of SCN7A cause changes in gastric cancer infiltrating immune cells to promote antitumor immune efficacy." (PMID 35123417, 2022).
lung carcinoma (1 paper, 2024). "By intersecting these top DEGs, we recognized seven genes potentially involved in the pathogenesis of both SSc and lung cancer: SCN7A, AGTR1, WIF1, PRKG2, LTF, AQP4, and COL10A1." (PMID 39744538, 2024).
melanoma (1 paper, 2023). A malignant, usually aggressive tumor composed of atypical, neoplastic melanocytes. "However, melanoma cells express negligible amounts of SCNA5 or SCN7A, another cardiac channel isoform." (PMID 37563469, 2023).
neuroblastoma (1 paper, 2014). Neuroblastoma (NB) is the most common solid, extracranial childhood tumor. "SCN7A and CHD5 have all been linked causally to neuroblastoma biology and prognosis." (PMID 25295525, 2014).
non-small cell lung carcinoma (1 paper, 2020). A group of at least three distinct histological types of lung cancer, including non-small cell squamous cell carcinoma, adenocarcinoma, and large cell carcinoma. "Recently, a new comprehensive bioinformatics study showed that low expression of SCN7A in non-small-cell lung cancer patients was associated with poor survival." (PMID 33102522, 2020).
pancreatic cancer (1 paper, 2023). "Moreover, an in silico analysis of TCGA pancreatic cancer dataset reported high expression levels of SCN7A in the high immune and stromal score groups, which were associated with better OS of the patients, suggesting the prognostic value of SCN7A for patients with pancreatic cancer." (PMID 36737824, 2023). "Since the currently available studies demonstrating the presence and role of SCN7A in Schwann cells, immune and stromal cells surrounding pancreatic cancer, it was speculated that the role of SCN7A may lie in the tumour microenvironment rather than the tumour cells." (PMID 36737824, 2023).
Pruritus (1 paper, 2026). Pruritus is an itch or a sensation that makes a person want to scratch. "Addressing these gaps will be crucial for enabling robust translational interpretations of rodent SGC studies—such as those presented here on an SCN7A+ SGC subpopulation selectively associated with NP neurons involved in pruritus." (PMID 41134052, 2026).
unipolar depression (1 paper, 2024). "Finally, SCN7A has been associated with unipolar depression and educational attainment." (PMID 38464225, 2024).
tumor (8 papers, 2009 to 2024). "For example, a recent study identified SCN7A as a key TMB-related gene in GC; the expression of SCN7A in tumor tissues was lower than that in normal tissues, and low SCN7A expression was relevant to better prognosis." (PMID 39323626, 2024). "To further analyze the effects of SCN7A in tumor-infiltrating immune cells, we calculated the correlation between SCN7A expression levels and TIICs." (PMID 35123417, 2022). "We found that the expression of SCN7A in tumor tissues was lower than that in normal tissues, and its expression level was also related to overall survival rate and tumor stage." (PMID 35123417, 2022). "Upon further exploration, a lower SCN7A DNA methylation level was shown with all probes in HCC tumour tissues based on the results of the SurvivalMeth online tool." (PMID 35126466, 2021). "The pan-tumour analysis showed that SCN7A expression was stably lower in tumours than SCN4A expression by TIMER." (PMID 35126466, 2021). "The mRNA expression of SCN4A was significantly higher at every grade, and the expression of SCN7A gradually decreased with the increase in tumour grade, but only significantly changed in grade 1 and grade 3." (PMID 35126466, 2021). "During this study, we made an interesting observation that the DNA methylation level of SCN7A was lower in tumours and that the mRNA expression of SCN7A was also lower in tumours." (PMID 35126466, 2021). "The only difference was that the levels of glycosylation markers were higher in tumours, while that of SCN7A was lower." (PMID 35126466, 2021). "The expression level of SCN7A in tumor tissues was lower than normal tissues." (PMID 35123417, 2022). "In addition, SCN7A expression was related to patient age (p < 0.001), satellite nodules (p = 0.028), tumour size (p = 0.001), adjacent organ invasion (p = 0.021), ICGI15 (p = 0.043), tumour grade (p = 0.034) and TNM classification (p < 0.001)." (PMID 35126466, 2021). "Furthermore, the expression of SCN7A was steady in most tumours, similar to glycosylation markers, which have already been used as cancer markers in the clinic." (PMID 35126466, 2021). "The DNA methylation level of SCN7A was low in tumours, and the lower methylation level might indicate a poor outcome." (PMID 35126466, 2021). "Therefore, the DNA methylation level and the mRNA expression of SCN7A could both be lower in tumours, and this result is consistent with the literature." (PMID 35126466, 2021). "Additionally, the expression of SCN4A was higher in tumours, while that of SCN7A was lower, suggesting that SCN4A and SCN7A might have different effects in HCC." (PMID 35126466, 2021). "The mRNA expression level of SCN4A/7A was also significantly related to individual tumour stages; similarly, SCN4A was highly expressed in every stage, but SCN7A expression decreased in stage 3 and stage 4." (PMID 35126466, 2021). "Although voltage-gated sodium channels have been reported to be involved in metastasis of various cancers, the direct role of SCN7A in PDAC tumour cells has not been described thus far." (PMID 36737824, 2023). "Taken together, it is conceivable that the EV PPP1R12A may reflect the effect of PDAC cells whereas SCN7A and SGCD may represent essential components from the tumour microenvironment, i.e., immune cells, fibroblasts and Schwann cells." (PMID 36737824, 2023). "Next, we performed a pan-tumour analysis of SCN4A and SCN7A in the TIMER database." (PMID 35126466, 2021).
tumor (continued). "The results of the UALCAN database had showed that SCN2A/4A/5A/8A mRNA were highly expressed in tumour tissues, while SCN1A/7A/11A mRNA were expressed at low levels (p < 0.05), furthermore, the expression of SCN4A and SCN7A had the similar levels in microarray analysis result." (PMID 35126466, 2021). "Interestingly the proton exchange transporter gene NHE1 (SLC9A1) that is important for tumour metastasis was down-regulated, as well as the sodium channel transporters SCN1A, SCNN1B and SCN7A." (PMID 19662092, 2009).
cancer (3 papers, 2021 to 2023). A tumor composed of atypical neoplastic, often pleomorphic cells that invade other tissues. "The mRNA expression of SCN4A and SCN7A in 38 types of cancers was detected and compared with that in normal tissues." (PMID 35126466, 2021). "Noticeably, we also identified upregulated expression of the sodium channel gene Scn7a in PEP1, which has been indicated to contribute to cancer pain by increasing excitability of neurons in DRG." (PMID 35722619, 2022). "From these results, we learned that expression of SCN7A was more stable and significantly lower in many types of non-cancer tissues compared to cancer tissues including HCC." (PMID 35126466, 2021).
cardiovascular disease (1 paper, 2012). "Although the biological function of Scn7a that encodes Nax (a sodium channel of voltage-gated sodium channel family) remains fragmental, our results prompt the potential role of Scn7a in DM-induced cardiovascular disease." (PMID 23227140, 2012).
SCN7A also shares sentences with these, for which no sentence is quoted: schizophrenia (2 papers); adenocarcinoma (1); amyotrophic lateral sclerosis (1); asthma (1); cannabis dependence (1); colon cancer (1); COVID-19 (1); dilated cardiomyopathy (1); epilepsy (1); Hypernatremia (1); hypertrophic cardiomyopathy (1); hypoplastic left heart syndrome (1); microcephaly (1); neurodegenerative disease (1); neurofibroma (1); Obesity (1); Parkinson disease (1); prostate carcinoma (1); prostate diseases (1); rectal cancer (1); Stroke (1); viral infection (1).